MMP9 (matrix metallopeptidase 9)
Diseases named in the same sentence as MMP9 in open-access papers (continued):
Sharing a sentence is not in itself a finding about the gene and the disease.
melanoma (continued). "Protein expression in the tumors and melanoma cells revealed the upregulation of MMP-9 and TGF-β1 after the transplantation of endothelial mitochondria." (PMID 38339136, 2024). "Vascular endothelial growth factor receptor 3 (VEGF R3) and metalloproteinase 9 (MMP-9) also reduced their expression in response to the sponge fraction in melanoma cells by about 50% (p < 0.05) and 30% (p < 0.01), respectively." (PMID 39000524, 2024). "Intra-tumorally administered CRAMP, the mouse ortologe of LL-37, significantly increased the mRNA expression of CXCL5, IL23A, MMP1a, and MMP9 in B16F10 melanoma." (PMID 36980564, 2023). "MMP-2 and MMP-9 are secreted by both melanoma cells and stromal cells in the tumor microenvironment." (PMID 37504268, 2023). "MMP-2 (matrix metalloproteinase-2) and MMP-9 (matrix metalloproteinase-9) have also been studied in the context of melanoma progression and metastasis." (PMID 37504268, 2023). "Several studies have shown that the expression and activity of MMP-2 and MMP-9 are increased in melanoma cells compared to normal skin cells." (PMID 37504268, 2023). "Quercetin was found to inhibit the invasion of murine melanoma B16-BL6 cells by decreasing pro-MMP-9 via the PKC pathway." (PMID 36829966, 2023). "Intra-tumor injection of LL-37 significantly increased CXCL5, IL23A, MMP1a, and MMP9 mRNA expression in mouse B16F10 melanoma." (PMID 36980564, 2023). "In colorectal cancer, HIF1A, MMP9, and PTGS2 had the highest mutation frequency at 5.8%, 7.7%, and 5.8%, respectively, while in melanoma, PPARG and TGFB1 had the highest mutation frequency at 4.7% and 1.9%, respectively." (PMID 37033970, 2023). "For example, osteopontin signaling increased the secretion of MMP-9 from TAMs to promote angiogenesis and tumor progression in a melanoma model." (PMID 36980564, 2023). "Levels of OPN and MMP9 were correlated and higher in melanoma patients than in controls but, in those patients with the V600E BRAF mutation, the levels of both OPN and MMP9 were not different than in those patients without that mutation." (PMID 37444590, 2023). "Metastatic murine melanoma cells were prevented from migrating towards the gel of basement membrane by carnosol and this effect was connected to the inhibition of MMP-9." (PMID 37803407, 2023). "For example, quercetin inhibits the invasion of murine melanoma cells by reducing pro-MMP-9 through the PKC pathway." (PMID 37927588, 2023). "The results obtained demonstrated that following the interaction with HUVEC cells, both drug-sensitive and -resistant melanoma cells were able to release MMP9 gelatinase." (PMID 37371639, 2023). "LL-37 increased the mRNA expression and protein production of CXCL5, IL-23p19, and MMP-9 in A375 human melanoma cell lines." (PMID 36980564, 2023). "Other commonly evaluated markers were some of those that have previously been reported as VM-associated in melanoma, including MMP-2, MMP-9, and EphA2." (PMID 36823554, 2023). "A specific role of MMP9, produced by melanoma or carcinoma cells, in the in vivo extravasation process across the BBB in the mouse model has been recently described." (PMID 37894438, 2023). "A previous study suggested that berberine suppressed the migration and invasion of A431 cells and also inhibited human melanoma A375.S2 cell migration and invasion via inhibition of MMP-9." (PMID 36770659, 2023). "Among the members of the MMP family, MMP‐2 and MMP‐9 have been reported to correlate with the invasive phenotype of melanoma." (PMID 37038620, 2023). "Emodin shows the anti-proliferation which is a time-dependent procedure and can prevent the MMP-9 effect of anti-melanoma." (PMID 37803407, 2023). "Upregulation of MMP9 has been found in the pre-metastatic niche and promotes pulmonary metastasis of melanoma (B16) and Lewis lung carcinoma (LLC) xenograft." (PMID 37443052, 2023).
melanoma (continued). "Cluster NR12 was specifically enriched for pathways involving extracellular matrix degradation and expressed several metalloproteinases including MMP9 which has been shown to mediate anti-PD1 resistance in melanoma." (PMID 36550535, 2022). "In further support of a resistance-promoting effect of CAFs, CAFs can mediate resistance to checkpoint blockade by secreting MMP-9, which can cleave PD-L1 from melanoma cells." (PMID 35558554, 2022). "We detected a higher level of MMP9 in CAKsCM treated with CM collected from Hs294T and in CAKsINS co-cultured with highly invasive melanoma cell lines (A375, WM9, Hs294T) in comparison to control cells." (PMID 36123693, 2022). "Exosomes produced from activated CD8+ T cells can activate ERK and NF-κB signaling pathways in melanoma cells, increasing the metastasis of cancerous cells in vitro by increasing matrix metalloproteinase-9 (MMP9) expression." (PMID 35550636, 2022). "MMP2 has been believed to act as a pro-tumorigenic and pro-metastatic factor in different cancers aside from melanoma, whereas higher MMP9 levels have been found in patients with melanoma than in healthy population, making it a promising marker for melanoma." (PMID 36387162, 2022). "Similar inhibition of MMP-9 expression in the presence of Tamarixetin was observed in A549 lung cancer cells as well as A375 melanoma cells." (PMID 35273218, 2022). "Our study verified that LH-1 induced apoptosis through the mitochondrial apoptosis pathway and inhibited the migration via downregulated expression levels of MMP-9 in melanoma cells." (PMID 36312981, 2022). "Last but not least, in obese patients, adipocytes participate in “tumour niche” establishment by synthesis of MMPs, especially MMP2 and MMP9, that mediate the remodelling of tumour extracellular matrix, thus promoting motility and invasion of melanoma cells." (PMID 35334544, 2022). "In melanoma cells (A375 and H1205-lu), the expression of MMP9 and AMPK decreased in A375 cells after stimulation with IL-10 (20 ng/mL), while BCL-2 did not change significantly." (PMID 35893303, 2022). "Overexpression of KYNU can promote changes in apoptotic BCL-2, metabolic KYN, 3-HAA, invasion and migration MMP9, E-cadherin, and other related proteins in melanoma." (PMID 35893303, 2022). "Our study agreed with the previous investigations that MMP2 and MMP9 can represent a biomarker of malignant melanoma, and downregulating MMP2 expression would increase prognostic survival." (PMID 36452505, 2022). "These membrane-bound proteins generate cytosolic ROS and upregulate EMT markers, such as MMP2 and MMP9 and, thus, contribute to melanoma invasion." (PMID 35406721, 2022). "MMP-9 has an important function in ECM degradation: MMP-9 activation enables the infiltration of melanoma cells into surrounding tissues and the subsequent spread of melanoma cells." (PMID 35925486, 2022). "For example, osteopontin signaling increased the secretion of prostaglandin E2 and MMP-9 from TAMs to promote angiogenesis and tumor progression in a melanoma model." (PMID 35409404, 2022). "Increased expression of pro-MMP2 and MMP-9 occurred in melanoma cell lines following ARSB silencing, and these increases were associated with increased invasiveness." (PMID 36361933, 2022). "Third, linc00673 is known to form a complex with androgen receptor (AR), and Brn3a activates matrix metalloproteinase 9 (MMP9), which has been shown to increase melanoma invasiveness." (PMID 34231850, 2021). "A similar phenomenon was observed in XBP1 overexpressed melanoma cells, wherein the increasing expression of XBP1 promotes melanoma cell proliferation by activating the AKT pathway associated with MMP2 and MMP9." (PMID 34484336, 2021). "The extracellular matrix (ECM)-degrading proteases comprising a disintegrin and metalloprotease-9 (ADAM9), matrix metalloproteinase-7 (MMP7), and MMP9 play a pivotal role during melanoma growth, migration, and adhesion." (PMID 34360915, 2021).
melanoma (continued). "Here, our result has added a novel case of MMP9 up-regulation in mouse melanoma cells to Nanog signaling." (PMID 33665763, 2021). "Odibenzo-p-dioxin (TCDD) exposure up-regulated the expression and activity of MMP9 in a variety of malignant tumors, including melanoma cells, urothelial cancer cells, prostate cancer cells, and gastric cancer cells." (PMID 34458309, 2021). "MMP‐9 was identified as a soluble sheddase in deteriorating T cell‐melanoma cell recognition by shedding natural killer group 2, member D (NKG2D) expressed in TILs and MHC class I expressed in melanoma cells." (PMID 34486239, 2021). "The cell-surface hyaluronan receptor, CD44, binds to MMP9 on melanoma cells and forms a CD44/MMP9 complex." (PMID 34207884, 2021). "Knowing that both TILs and melanoma cells were the primary targets of the MMP‐9, we next devoted our efforts to define cell surface molecules that were affected by MMP‐9 in these cells." (PMID 34486239, 2021). "Together, these findings provide compelling evidence that MMP‐9 released by IL‐33‐stimulated macrophages mediates the immunosuppressive effects and protects melanoma cells from the STIL‐executed killing." (PMID 34486239, 2021). "Extracellular acidosis also activates phospholipase D, ERK1/2, p38 MAPK, and NF-κB in metastatic mouse melanoma, which induces MMP9 expression in cancer cells." (PMID 33918883, 2021). "This complex in turn binds to MMP9 promoter, activating the expression of matrix metalloproteinase 9, thus promoting melanoma cell invasion." (PMID 34638331, 2021). "In the lungs of patients diagnosed with esophageal cancer, melanoma and ovarian cancer, a high expression of MMP-9 was found, which suggests that primary tumors can stimulate the production of MMP-9 in premetastatic areas." (PMID 34204372, 2021). "Complementary, in melanoma cancer, FOXD1 was critically involved in invasion and migration via indirect regulation of RAC1b and MMP-9 alternative splicing in melanoma cells." (PMID 34772357, 2021). "In line with this work, it was demonstrated that Let‐7i regulates cell migration of melanoma cells via directly targeting MMP‐9 in vitro." (PMID 34096173, 2021). "LNMAT knockdown results in decreased matrix metalloproteinases MMP2 and MMP9 expression and inhibits invasion and migration of melanoma cells." (PMID 34638331, 2021). "In our previous study, it had been shown that CAFs can facilitate melanoma angiogenesis, and the expression of the angiogenic factor MMP9 in CAFs is upregulated compared with that in NFs." (PMID 34327132, 2021). "Taken together, these in vivo experiments demonstrate that MMP‐9 is the key mediator of immunosuppression by IL‐33‐macrophages and it targets both STILs and melanoma cells." (PMID 34486239, 2021). "TCDD exposure up-regulated the expression and activity of MMP9 in various malignancies including melanoma cells, urothelial cancer cell, prostate cancer cell, and gastric cancer cell." (PMID 33542896, 2020). "Of these peptidases, MMP-9 is the most involved in the development of cancer, including that of melanoma." (PMID 32392801, 2020). "Since both FAK and MMP-9 have been previously related to the invasive properties of melanoma cells, our results further support the anti-invasive properties of CAXII inhibition." (PMID 33080820, 2020). "Providing further evidence in support of GLO1 expression as a mechanistic determinant of melanoma cell invasiveness, differential expression of MMP9 as a function of GLO1 status was substantiated by enzymatic activity and ELISA analysis." (PMID 32466621, 2020). "This was also accompanied by disruption of the BM, likely due to BM breakdown via MMP-9 produced by melanoma cells." (PMID 32507967, 2020). "Curcumol upregulated the expression of E-cadherin and downregulated the expression of N-cadherin, MMP2 and MMP9 in mouse melanoma B16 cell." (PMID 32194780, 2020).
melanoma (continued). "In summary, this is the first report showing nuclear-localized DLC1 to function as an oncogene through FOXK1 recruitment to cooperatively transactivate MMP9 expression for promoting melanoma invasion and metastasis." (PMID 32214200, 2020). "To correlate the clinical relevance of DLC1, FOXK1, and MMP9 expression, we analyzed their expression in a melanoma tissue microarray composed of 50 cores of metastatic melanomas." (PMID 32214200, 2020). "Overall, our results indicate that interaction between Tspan8+ melanoma cells and neighboring keratinocytes are essential to drive MMP-9 activation, collagen IV dissolution, and subsequent dermal invasion." (PMID 32455575, 2020). "A similar effect was observed for other melanoma cell lines, although it is difficult to interpret due to the very low expression of MMP-9." (PMID 31586300, 2020). "RNA-sequencing profiling studies further revealed MMP9 as a direct target of FOXK1 through DLC1-regulated promoter occupancy for cooperative activation of MMP9 expression to promote melanoma invasion and metastasis." (PMID 32214200, 2020). "Our data, together with the data available in the literature, reveal that Tspan8 expression in melanoma cells promotes the activation of keratinocyte-generated proMMP-3 in the stroma, which engages MMP-9 activation and DEJ proteolysis." (PMID 32455575, 2020). "Functional and mechanistic studies revealed SLNCR1 promotes melanoma invasion through upregulation of MMP9 (involved in ECM degradation) in cooperation with the brain-specific homeobox protein 3a (Brn3a) and the androgen receptor (AR)." (PMID 33203119, 2020). "The regulatory relationship between nuclear DLC1–FOXK1 complex and MMP9 is further supported by a strong correlation of their expression in metastatic melanomas as well as a panel of melanoma cell lines." (PMID 32214200, 2020). "Concerted action of DLC1–FOXK1 in MMP9 gene regulation was further supported by their highly correlated expression in melanoma patients’ samples and cell lines." (PMID 32214200, 2020). "This implies that MMP-9 expression by melanoma cells is acquired after dermal invasion and local dissemination." (PMID 32455575, 2020). "MMP-9 knockdown can reduce the migration and invasion of melanoma cells and inhibit epithelial-mesenchymal transformation (EMT), thus being considered as a promising molecule for the CM treatment." (PMID 33240619, 2020). "IGF2BP3 promotes trophoblast invasion and migration via MMP9 mRNA stabilization and translation, and melanoma invasion and migration via HMGA2 mRNA stabilization and translation." (PMID 32293476, 2020). "Accordingly, a Tspan8-specific antibody efficiently targeting in vivo Tspan8+ melanoma xenografts was able to reduce MMP-9 activity, DEJ breakdown, and dermal invasion." (PMID 32455575, 2020). "Our data showed that shikonin inhibited the expression levels of antiapoptotic proteins Bcl-2 and Mcl-1, and enzymatic activities of collagenases MMP-2 and MMP-9, which play vital roles in melanoma metastasis." (PMID 32536866, 2020). "Previous work described how quercetin and sulforaphane were able to reduce melanoma growth in a mouse model by suppressing MMP-9 expression in the mouse tumours." (PMID 32545262, 2020). "Consistently, DLC1, FOXK1, and MMP9 exhibited a high correlation of expression in melanoma patients’ samples and cell lines." (PMID 32214200, 2020). "Nevertheless, the DLC1–FOXK1 complex further augmented the degree of transactivation of MMP9 gene expression as well as melanoma invasion and metastasis." (PMID 32214200, 2020). "The decrease in MMP2 and MMP9 following curcumol-treated mouse melanoma B16 cells was markedly attenuated by the miR-152-3p inhibitor." (PMID 32194780, 2020). "ATX down-regulated MMP-1, MMP-2, and MMP-9, resulting in the inhibition of migration and invasion of melanoma cells in a dose-dependent manner from 5 – 125 μg/ml for 24 h." (PMID 32711429, 2020).
melanoma (continued). "Therefore, the evaluation of MMPs circulating levels, and in particular the use of OPN and MMP-9 as circulating biomarkers, may improve the current diagnostic strategies for melanoma and predict the aggressiveness of tumors, in order to personalize the therapeutic approach for the patients." (PMID 32392801, 2020). "This indicates that Tspan8+ melanoma cells, once invading the dermis, acquire the capability of expressing the precursor forms of MMP-9 and MMP-3, which were previously provided by the keratinocytes when situated in the epidermis." (PMID 32455575, 2020). "CAF-derived MMP-9 is an enzyme responsible for proteolytic PD-L1 cleavage from the surface of melanoma cells and, therefore, leads to anti-PD-1 therapy resistance." (PMID 33171792, 2020). "In particular, MMP‐2 and MMP‐9 are well‐known to induce cancer progression and the metastasis of melanoma through the degradation of Type IV collagen, which is the major component of the basement membrane." (PMID 31486124, 2019). "The present study showed reduced nuclear expression of Snail by cirsiliol which was further supported by the retarded expression and activity of MMP-9 in FN-induced melanoma cells." (PMID 30708951, 2019). "T cell-derived exosomes have been shown to promote the invasion and metastasis of melanoma and lung cancer by increasing matrix metalloproteinase-9 (MMP-9) expression through Fas/FasL-dependent ERK and NF-kB activation." (PMID 31615107, 2019). "Our qPCR results showed that BMP4 was down-regulated and MMP9 was up-regulated in melanoma tissue samples." (PMID 31569419, 2019). "A PI3K/mTOR inhibitor, GSK2126458A, given in combination with dabrafenib efficiently counteracted the stimulating effects of a BRAF inhibitor on invasiveness, and VEGF-A and MMP-9 secretion in A375R melanoma cells resistant to darafenib." (PMID 31295843, 2019). "A key role played by MMP9 was demonstrated in studies that showed that this protease promotes melanoma invasiveness by degrading components of the extracellular matrix." (PMID 31623313, 2019). "A key role for MMP9 was demonstrated in studies that showed that this protease promoted melanoma invasiveness by degrading components of the extracellular matrix." (PMID 31623313, 2019). "Upregulation of matrix metalloproteinases (MMPs), especially MMP2 and MMP9, appears to be particularly important in melanoma invasiveness." (PMID 31623313, 2019). "Further, doxycycline-inducible expression of CD133 increased melanoma invasion and levels of endogenous and secreted MMP9." (PMID 31623313, 2019). "Overexpression of matrix metalloproteinases, especially MMP2 and MMP9 appear to be particularly important in melanoma invasiveness." (PMID 31623313, 2019). "The degradation of ECM by MMPs mainly MMP‐2 and MMP‐9 have been consistently correlated with migration, invasion, and adhesion as well as angiogenesis in many types of cancer including melanoma (Akhavan, Karimi, Ghodrati, & Falahtpishe, 2011)." (PMID 30653763, 2019). "In direct support of an oncogenic function for AR, we recently showed that AR increases melanoma invasion through transcriptional upregulation of the matrix metalloproteinase MMP9." (PMID 31116991, 2019). "SLNCR1, AR, and Brn3a are specifically required for transcriptional activation of matrix metalloproteinase 9 (MMP9) and increased melanoma invasion." (PMID 31921860, 2019). "Independent knockdown of either MMP-9 or Madcam1 by shRNA in melanoma cells inhibited EMT and invasion induced by TRIM59-/--M2 macrophage CM, and attenuated the growth of subcutaneous B16-F10 tumors and reduced lung metastasis burden in TRIM59-CKO-mice." (PMID 31600735, 2019). "Our study showed that TNF-α promoted the expression of MMP-9 and Madcam1 in melanoma cells, which contributed to melanoma growth and metastasis." (PMID 31600735, 2019). "Acid extracellular pH has been found to increase intracellular Ca2+and matrix metalloproteinase-9 (MMP-9) expression in the mouse B16 melanoma (ME) model." (PMID 31801263, 2019).